IGF1 (insulin like growth factor 1)
Diseases named in the same sentence as IGF1 in open-access papers (continued):
Sharing a sentence is not in itself a finding about the gene and the disease.
Obesity (continued). "The relationship between obesity and IGF-1 levels remains a topic of controversy, as different studies have reported higher, lower, or comparable IGF-1 levels in obese children compared to nonobese children." (PMID 37111069, 2023). "The progression of HCC due to insulin and insulin-like "growth factor 1" (IGF-1) exhibits its proliferative effects on cells, oncogenic effects of hyperglycemia, and obesity." (PMID 37065332, 2023). "The major contributing factors of obesity and T2D/IGT that influence the risk of cancer were increased levels of growth factors such as insulin, IGF-1, steroid and peptide hormones, and inflammatory markers." (PMID 37511200, 2023). "The mechanism responsible for the altered GH and IGF1 secretion observed in obesity is largely unclear." (PMID 37892272, 2023). "In individuals with obesity, lower IGF-1 serum levels and a blunted response to GH-stimulating dynamic tests are associated with more significant metabolic impairment and even morpho-functional cardiological alterations." (PMID 36851702, 2023). "Only through comprehensive research involving human populations can we confidently assess the feasibility and suitability of GH and IGF-1 therapies as effective strategies for combating obesity." (PMID 37298507, 2023). "HFD usually leads to obesity, which results in hyperinsulinemia and increased amounts of circulating bioactive insulin-like growth factor-1 (IGF-1) that has the ability to promote the development of many types of cancer." (PMID 36675055, 2023). "This review aims to evaluate the therapeutic potential of targeting the GH and IGF-1 axis in the management of obesity by examining their interaction with metabolism." (PMID 37298507, 2023). "In this review, we summarized the effects of obesity and IGF-1 on cognitive function, and discusses the mechanism by which exercise improved ORCD through regulating IGF-1." (PMID 37638322, 2023). "Patients with obesity also have higher insulin levels, leading to increased IGF-1 in breast cancer cells, which activates the PI3K/AKT/mTOR and RAS/RAF/MAPK signaling pathways that result in endocrine therapy resistance." (PMID 37173991, 2023). "IGF-1 is a key predictive factor for metabolic alterations in obesity as it represents a mitogenic hormone involved in processes like growth, angiogenesis, and differentiation." (PMID 36851702, 2023). "Obesity is also a disease characterized by the presence of low-grade chronic inflammation, and the recovery of normal IGF-1 synthesis over time after BS was reported to be independently related with CRP." (PMID 36904198, 2023). "High-protein intake during infancy may increase weight gain and obesity risk in later years and observational studies have found an increased risk for the development of NCDs, because of the elevated levels of insulin and of insulin-like growth factor-1 (IGF-1)." (PMID 38201860, 2023). "IGF-1 is also closely related to the occurrence and development of diseases such as diabetes, obesity, and metabolic syndrome." (PMID 37266131, 2023). "It is important to approach the use of GH and IGF-1 in obesity management with caution, considering the potential risks and limitations that are associated with their use." (PMID 37298507, 2023). "Randomized, controlled trials are needed to confirm the efficacy of GH and IGF-1 targeted therapies in treating obesity and determine their long-term safety." (PMID 37298507, 2023). "Obesity can trigger an increase in the levels of insulin and insulin-like growth factor 1 (IGF-1) in the blood." (PMID 37835359, 2023). "Disorders of insulin, IGF-1, sex hormones, adipokines and inflammatory factors have been observed in numerous studies in the presence of obesity." (PMID 36755926, 2023). "A previous study aimed to investigate the potential role of GH and IGF-1 in the development of obesity and focused on their role in mediating oxidative stress and inflammation." (PMID 37298507, 2023).
Obesity (continued). "The aim of the study was to evaluate circulating insulin‐like growth factor‐1 (IGF‐1) in non‐diabetic cats with overweight/obesity and to screen this population for the presence of HST." (PMID 38053473, 2023). "While some studies suggest an interrelation between vitamin D status, IGF1, and obesity, this mechanism remains obscure." (PMID 37892272, 2023). "Our results demonstrate that the IGF-1 pathway is the main metabolic target for the anti-obesity effect of BPL1TM and LTA from BPL1TM while the genes jnk-1 and pmk-1, belonging to the JNK-1/DAF-16 pathway and p38 MAPK pathway, respectively, are not required." (PMID 38136226, 2023). "This review of the literature highlights the potential therapeutic benefits of targeting GH and IGF-1 in the management of obesity." (PMID 37298507, 2023). "This review article aims to provide a comprehensive view of the interplay between GH and IGF-1 and metabolism within the context of obesity." (PMID 37298507, 2023). "Several mechanisms focusing on the role of leptin, adiponectin, insulin-like growth factor-1 (IGF-1), and inflammatory cytokines have been proposed to explain the effects of obesity on CCA." (PMID 36766711, 2023). "Obesity is a growing public health problem worldwide, and GH and IGF-1 have been studied as potential therapeutic targets for managing this condition." (PMID 37298507, 2023). "Second, the study did not collect data on different types of obesity, making it difficult to determine the relationship between different types of obesity and IGF-1 levels." (PMID 37111069, 2023). "This article reviews the effects of obesity and IGF-1 on cognitive function and the regulation of exercise on IGF-1." (PMID 37638322, 2023). "The PI3K/Akt/mTOR pathway is activated by several upstream triggers, such as insulin-like growth factor 1 (IGF-1), insulin, and physical activity, all of which are associated with obesity or aging." (PMID 37237929, 2023). "lactis BPL1, reduced obesity biomarkers in Caenorhabditis elegans under hyperglycemic conditions via the IGF-1 pathway." (PMID 37935755, 2023). "The study provides new insights into the relationship between obesity and related chronic diseases, particularly the potential role of IGF-1 levels as an early warning indicator." (PMID 37111069, 2023). "Our results suggest a possible mechanism for the interrelations between IGF1, vitamin D, and obesity." (PMID 37892272, 2023). "First, this study found lower GH concentrations in humans with obesity than in lean humans in the setting of similar IGF-1 concentrations, indicating a preserved IGF-1 feedback mechanism." (PMID 36959287, 2023). "Future studies should be conducted for repurposing sustained augmentation of IGF-1 with the supplement in weight control, and to assess its benefits in otherwise healthy individuals with obesity and low-normal hGH." (PMID 36998474, 2023). "Obesity induces adipocyte stress and increases lipolysis while IGF1 (in vitro) regulates differentiation, promotes survival and suppresses lipolysis of adipocytes." (PMID 36722834, 2023). "The increased musculoskeletal problems in diabetics are related to neuropathy, vascular insufficiency, decreased insulin-like growth factor 1, obesity, accelerated osteoporosis, and a sedentary lifestyle." (PMID 38584997, 2023). "Several maternal obesogenic factors contribute to obesity in offspring, including glucose, FFAs, insulin, leptin, IGF-1 and adiponectin." (PMID 36329895, 2022). "In the present study, skeletal muscle IGF‐1, Wnt3a, Wnt5a and Wnt7a mRNAs were all reduced in subjects with obesity." (PMID 35293040, 2022). "Nevertheless, higher protein intake is thought to increase insulin and insulin-like growth factor-1 (IGF-1) secretion in early childhood, which is associated with early obesity rebound." (PMID 35631148, 2022). "Obesity, both before and/or during pregnancy, a condition related to consumption of energy-dense diets, can alter IGF-1 secretion and actions, leading to GDM." (PMID 35813659, 2022).
Obesity (continued). "A major consequence of obesity is hyperinsulinemia, which drives both systemic and local production of IGF-1 and IGF-2 and increases IGF bioavailability by suppressing IGFBP expression." (PMID 36556357, 2022). "The distinctive features of LS are short stature (−4 to −10 SDS below median height), typical face, reduced head circumference, obesity, high basal serum GH and low to undetectable serum IGF1." (PMID 35626664, 2022). "Children with obesity have more receptors for growth hormone (GH), higher levels of insulin-like growth factor-1 (IGF-1), and higher levels of leptin and insulin." (PMID 36554686, 2022). "These events appear to affect myokines that are effective in sarcopenic obesity such as IL-6, IL-10, IL-15, myostatin, insulin-like growth factor (IGF-1), irisin, and fibroblast growth factor-21 (FGF-21)." (PMID 35250869, 2022). "Growth hormone’s effects are mediated by IGF-1, the synthesis of which is shown to be upregulated in both hypertension and overweight/obesity." (PMID 35371887, 2022). "The diet and particularly proteins, dietary restrictions, obesity, and lifestyle influence the level of IGF‐1." (PMID 35048526, 2022). "IGF-1 has also been linked to carcinogenesis; however, in contrast to insulin, there is much debate surrounding circulating total IGF-1 levels and obesity in humans." (PMID 36038791, 2022). "In individuals with obesity, lower IGF-1 serum levels and a blunted response to growth hormone-stimulating dynamic tests are associated with greater metabolic impairment." (PMID 35057554, 2022). "The present study demonstrates that obesity alters skeletal muscle‐derived small EV miRNAs targeting many inflammatory and anabolic pathways, including the Wnt/β‐catenin and IGF‐1 signalling pathways." (PMID 35293040, 2022). "Accordingly, obesity is characterized by increased levels of circulating factors including insulin, insulin-like growth factor 1 (IGF-1), leptin, and inflammatory cytokines such as IL6 and TNFα." (PMID 36010901, 2022). "Herein, we examined the distribution of IGF-1 SDS values in Japanese subjects with BMI ≥ 35 kg/m2, since this level of obesity is known to be a risk factor for a range of diseases in the Japanese population." (PMID 36418379, 2022). "Adipocytokines, such as adiponectin, leptin, and IGF-1 are key regulators of energy metabolism and fat stores that are centrally involved in the pathomechanistic sequaele of adipositas and obesity." (PMID 34319428, 2022). "In our pediatric population, IGF1 levels are lower in patients with high BMI and with significant obesity (r = −0.15, p = 0.03)." (PMID 36557260, 2022). "Since systemic inflammation is an important mediator of impaired insulin and IGF-1 signaling in obesity, we next assessed systemic inflammatory markers." (PMID 35628414, 2022). "After a decrease in body adiposity in the first months of IGF1 treatment, a progressive increase in obesity usually occurs." (PMID 35283485, 2022). "In conclusion, obesity alters the miRNA content of small skeletal muscle‐derived EVs targeting several growth and inflammatory pathways, including the anabolic pathways IGF‐1 and Wnt/β‐catenin." (PMID 35293040, 2022). "Exercise studies showed that at week 8 training, the serum concentration of IGF-1 in the resistance training group is higher in sarcopenic obesity patients than the control group, while the combined training was superior to the endurance and control groups." (PMID 35250869, 2022). "Cell growth in ovarian cancer cells has been shown to be promoted by IGF-1, which is usually related to obesity and hyperinsulinism." (PMID 34751020, 2022). "First, obesity-related GH resistance in the liver, such as that characteristic of fatty liver, reduces IGF-1 production, leading to decreased serum IGF-1 levels." (PMID 36418379, 2022).
Obesity (continued). "Obesity also decreases the levels of these IGFBPs, thus increasing the bioavailability of IGF-1, promoting an increase of nutrient availability to the fetus, which can lead to overgrowth and other metabolic complications, characteristics of GDM." (PMID 35813659, 2022). "MiRNAs identified to be up‐regulated in both obesity and sarcopenia target IGF‐1, leading to its inhibition." (PMID 34984856, 2022). "In this regard, when added IGF-1 zSDS as a variable, our second model increased its precision, reaching the value of 71.84% for the presence of metabolically healthy obesity and 72.3% for its absence." (PMID 35057554, 2022). "Obesity-related alterations of insulin/IGF-1 signaling as well as premature aging processes are significantly caused by a prevailing systemic inflammation, the latter being known as ‘inflamm-aging’." (PMID 35628414, 2022). "Both GH and IGF-1 play a role in the cycle of exacerbating obesity, and exploring the 11ß-hydroxysteroid dehydrogenase type 1 (11ß-HSD-1) enzyme can provide a better understanding." (PMID 35887957, 2022). "We found that gene expression of GHR, IGF-1 and IGFBP-3 was compromised in AT of children with overweight/obesity and was associated with parameters of adipocyte function such as adipocyte hypertrophy and increased fasting insulin levels." (PMID 36384443, 2022). "A total of 24 osteoporosis-related genes, including IGF1, IL6, pyruvate dehydrogenase kinase 4 (PDK4), PPARGC1A, and TF, were also associated with obesity and diabetes." (PMID 35328013, 2022). "Circulating insulin and insulin-like growth factor-1 have been identified as factors that mediate obesity-dependent cancer progression." (PMID 36428776, 2022). "Myokines affecting sarcopenic obesity include IL-6, IL-10, IL-15, myostatin, insulin-like growth factor (IGF-1), irisin, FGF-21, and leukemia inhibitory factor (LIF)." (PMID 35250869, 2022). "Biological pathway analysis found that obesity alters the expression of small EV miRNAs targeting components of the IGF‐1 and Wnt/β‐catenin signalling pathways." (PMID 35293040, 2022). "One of the key predictive factors for metabolic disruption in obesity is insulin-like growth factor 1 (IGF-1), a mitogenic hormone involved in several processes like growth, angiogenesis and differentiation." (PMID 35057554, 2022). "Patients with obesity and low IGF-1 concentrations have considerably more visceral obesity than patients with obesity and normal IGF-1 concentrations." (PMID 36120463, 2022). "In fact, we also found in early-pubertal girls with obesity a significant correlation between IGF-1 and androgen levels (DHE-S, androstenedione and testosterone)." (PMID 35412268, 2022). "IGFBP-2 has been shown to decrease in obesity and hyperinsulinemia, potentially increasing the levels of free IGF-1." (PMID 36038791, 2022). "Fat and skeletal muscle are the primary target organs of the GH/IGF-1 axis, and play a key role in the pathophysiology of type 2 diabetes and obesity." (PMID 36120463, 2022). "Obesity has been shown to increase the secretion of androgens, insulin, insulin-like growth factor 1 (IGF-1), and growth hormones." (PMID 36694512, 2022). "Increased levels of insulin, triglyceride, total cholesterol, LDL cholesterol, CRP-U, AST, ALT, GGT, free T4, IGF-1, and uric acid and low levels of HDL cholesterol are found to be associated with a higher chance of obesity." (PMID 35703718, 2022). "Obesity-dependent cancer development and progression involve inflammation, adipokines, microbiota, hyperinsulinemia, and IGF-1 signaling, which has been extensively summarized and reviewed." (PMID 36428776, 2022). "Obesity has a direct effect on certain hormone levels, such as insulin, oestrogen, and insulin-like growth factor-1, which produce a favourable environment for carcinogenesis." (PMID 36517625, 2022).
Obesity (continued). "Recently, we reported that skeletal muscle IGF‐1 mRNA and protein and the mRNA expression of key Wnt ligands are reduced at rest and after acute resistance exercise in humans with obesity." (PMID 35293040, 2022). "ASCs also show increased expression of IGF-1 in obesity, enhancing local invasion in mice possibly through its effect on anoikis (elaborated later in this section)." (PMID 36038791, 2022). "The rationale for this selection is the fact that endometrial cancer has been strongly correlated with obesity and diabetes and, furthermore, seems to be affected by circulating insulin/IGF1 levels." (PMID 35626664, 2022). "Evidence supporting the involvement of two recently recognized factors linking obesity to neurodegeneration is based on the induction of proinflammatory cytokines and resistance to insulin-like growth factor 1 (IGF-1)." (PMID 34327017, 2021). "Laron syndrome (LS), the best characterized entity under the spectrum of the congenital IGF1 deficiencies, results from mutation of the GH receptor (GHR) gene, leading to dwarfism, obesity and other defects." (PMID 34769292, 2021). "IGF1 is a polypeptide that is structurally similar to human pro-insulin, which is one of the pathogenetic factors resulting in obesity and other diseases." (PMID 34544905, 2021). "Early work on IGF-1 concentrations in obesity showed that IGF-1 levels are inversely proportional to BMI." (PMID 34208601, 2021). "During puberty, differences in growth velocity between normal-weight and with obesity groups corresponded to differences in testosterone levels in boys and in estradiol in girls and resembled the pattern of the IGF-1 levels." (PMID 34386750, 2021). "Anthropometric parameters, levels of serum analytes related to obesity and Ins-R, and the esophageal insulin/IGF-1 signaling pathway were analyzed." (PMID 34684639, 2021). "The study results indicate that in obesity, high levels of insulin and IGF-1 enhance intestinal epithelial crypt proliferation through PI3K/AKT, without involvement of the ERK signaling pathway." (PMID 34659571, 2021). "Visceral fat is the key adipose compartment linking obesity to carcinogenesis, through increased systemic inflammation, insulin resistance, IGF-1, and immune cell alterations, as well as promoting inflammation in the TME." (PMID 33777773, 2021). "Although the role of insulin and IGF-1 in regulating metabolism in response to nutrients is well known, the role of IGF-1 in obesity mechanisms and IR is less described." (PMID 34208601, 2021). "Unfortunately, our sample size of IGF-1 in children younger than the age of 6 years was too low for the group with obesity to perform more detailed statistical analyses in order to determine the associations of increased IGF-1 on growth in early childhood." (PMID 34386750, 2021). "During pregnancy, MSG consumption induces obesity with downregulation of growth hormones, insulin-like growth factor-1 (IGF-1), reduces IntelliCage place learning and cue discrimination, impairs seizure threshold." (PMID 34026558, 2021). "The typical features of LS are short stature, typical face, obesity, high basal serum GH and low IGF1, unresponsive to the administration of exogenous GH." (PMID 34769292, 2021). "Insulin-like growth factor 1 (IGF-1) is the most studied insulin-like peptide in terms of its function in obesity, MS, IR, and cancer." (PMID 34830295, 2021). "Higher levels of IGF-1 are observed in both obesity and meningiomas, suggesting a role in the development of these tumors." (PMID 33801089, 2021). "Our study showed that upregulation of the IGF1/IGF1R signaling pathway protected the miR-379/miR-544 cluster KO mice against high-fat diet-induced obesity." (PMID 34527673, 2021). "Hypernutrition and hyperinsulinemia of obesity directly promote hepatic IGF-1 release and inhibit GH secretion." (PMID 34208601, 2021).